TLR9 (toll like receptor 9)
Diseases named in the same sentence as TLR9 in open-access papers (continued):
Sharing a sentence is not in itself a finding about the gene and the disease.
breast cancer (continued). "Hypoxia was included in these studies, as the cancer microenvironment becomes hypoxic upon tumor progression, and hypoxia regulates TLR9 expression in breast cancer." (PMID 39644451, 2024). "Although hypoxia, ERα and testosterone affect TLR9 expression in breast cancer, regulation of TLR9 expression in breast cancer remains poorly understood." (PMID 39644451, 2024). "To study the effect of HPV on TLR9 expression, we transduced parental human MDA-MB-231 and T-47D breast cancer cells with lentiviruses encoding the HPV16 E6 protein." (PMID 39644451, 2024). "Human papillomavirus (HPV) infections suppress TLR9 expression in cervical cancers but the association between HPV and breast cancer has remained controversial." (PMID 39644451, 2024). "The activation of TLRs, including TLR9, in plasmacytoid dendritic cells can inhibit breast cancer cell growth by directly killing tumor cells and activating NK cells and CD8+ T cells." (PMID 38903515, 2024). "The aim of this study was to test if HPV16 can suppress TLR9 expression in breast cancer cells and affect cell behavior." (PMID 39644451, 2024). "For example, TLR9 has been found to be expressed in human breast cancer cells and clinical breast cancer samples and TLR9 agonists can promote cellular invasion by increasing matrix metalloproteinase activity in breast cancer cells." (PMID 38903515, 2024). "Toll-like receptor 7 (TLR7) and TLR9 (TLR9) agonist intratumoral injection increases tumor-associated monocyte infiltration and TAM phenotypic modification in a mouse model of breast cancer." (PMID 37138860, 2023). "TLR2/4 are dominant in gastrointestinal cancers, like esophageal cancer, GC, and colon cancer, while TLR9 signaling is more common in other kinds of cancers, like breast cancer, prostate cancer, and renal cell carcinoma." (PMID 37153547, 2023). "The expression of TLR-9 is diminished in breast cancer and renal cell carcinoma, and higher expression of TLR-9 corresponds with better clinical outcomes." (PMID 36499102, 2022). "Various levels of TLR9 expression have been demonstrated in tumour specimens from patients with prostate cancer, breast cancer, astrocytoma, lung cancer and glioblastoma." (PMID 33336901, 2021). "Some experiments have validated that combined with the block in IL-10 receptor, the TLR9 agonist can reverse M2 polarization in breast cancer and colon cancer." (PMID 33407720, 2021). "In similarity to TLR3, there are also some studies reporting the importance of TLR9 in the regulation of lipid peroxidation in patients with breast carcinoma." (PMID 33336901, 2021). "Recent studies reported that TLR9 is also expressed in some types of tumor cells, including oral cancer, breast cancer, glioma and pancreatic cancer cells." (PMID 31892973, 2020). "In studies on TLRs and cancer, TLR9 is also expressed in lymphoma cells including oral cancer, breast cancer, glioma and pancreatic cancer cells." (PMID 31892973, 2020). "In the DA3 breast cancer model, DaRT combined with the TLR9 agonist CpG further retarded tumor growth compared to each treatment alone." (PMID 31637474, 2019). "Thus, this TLR9 variant may be a previously unknown source of health disparity in breast cancer." (PMID 28886076, 2017). "We conclude that decreased TLR9-expression sensitizes breast cancer cells to the growth inhibitory effects of bisphosphonates." (PMID 27888633, 2016). "Specifically, low tumor TLR9 expression confers increased cellular sensitivity to the growth inhibitory effects of BPs in breast cancer." (PMID 27888633, 2016). "TLR3 and -4 were identified as predictors of poor survival in breast cancer, whereas high TLR9 predicted enhanced survival." (PMID 27941651, 2016). "We demonstrate here for the first time that decreased TLR9 expression sensitizes breast cancer cells to the growth inhibitory effects of both p- and n-BPs." (PMID 27888633, 2016).
breast cancer (continued). "With respect to gene expression control, granulin is known to be able to activate PKC pathway and Toll-like receptor 9 signaling or interact with transcriptional factor such as STAT3 in breast cancer cells." (PMID 27598941, 2016). "First, the role of TLR9 as a biomarker for adjuvant BP efficacy should be studied in clinical breast cancer trials." (PMID 27888633, 2016). "Our results suggest that TLR9 should be studied as a potential biomarker for adjuvant bisphosphonate sensitivity among breast cancer patients." (PMID 27888633, 2016). "In conclusion, low tumor TLR9 expression sensitizes breast cancer cells to the growth inhibitory effects of BPs in vitro and in vivo." (PMID 27888633, 2016). "Our results suggest that tumor TLR9 expression status should be investigated as a potential biomarker for adjuvant BP use in breast cancer." (PMID 27888633, 2016). "Although TLR9 regulates tumor invasion in variety of cancer cells, including breast cancer, prostate cancer and colorectal cancer, the signaling pathways of TLR9 in invasion and migration of cancer remains incompletely understood." (PMID 26087186, 2015). "There was also an increase in the expression of TLR4 by mononuclear inflammatory cells and TLR9 by fibroblast-like cells in mammary tumors." (PMID 24904578, 2014). "Although TLR9 is widely expressed in breast cancers, it appears that tumor TLR9 expression has prognostic significance only in TNBC." (PMID 25101078, 2014). "In this review, we discuss the possible contribution of tumor TLR9 to the pathogenesis and treatment responses in breast cancer." (PMID 25101078, 2014). "We demonstrated recently that self-DNA, which is derived from doxorubicin-killed breast cancer cells, induces mRNA expression of various inflammatory mediators in living, TLR9-expressing cells." (PMID 25101078, 2014). "Down-regulation of TLR9 in MDA-MB-231 breast cancer cells through siRNA results in decreased in vitro invasion in the absence of exogenous DNA." (PMID 25101078, 2014). "Specifically in breast cancer, TLR9 protein expression has been detected both in the epithelial cancer cells as well as in the fibroblast-like cells associated with the tumors." (PMID 25101078, 2014). "Effective immunotherapy using combination of HER-2/neu genetic vaccine and novel agonist of TLR9 has been reported for breast cancer." (PMID 24904578, 2014). "Both estradiol and testosterone induced TLR9 expression via their cognate receptors in breast cancer cells in vitro." (PMID 25101078, 2014). "We demonstrated recently that although widely expressed in all clinical subtypes of breast cancer, TLR9 expression has significant, prognostic significance only in TNBC that lack the expression of estrogen (ER), progesterone (PR), and HER2 receptors." (PMID 25101078, 2014). "TLR9 isoforms A and B has been detected in clinical breast cancer, and ERα and sex steroid hormones have been shown to contribute to its invasiveness." (PMID 24904578, 2014). "Of the five human TLR9 isoforms (A–E), mRNA expression of the TLR9 A and B isoforms has been studied and detected in breast cancer specimens." (PMID 25101078, 2014). "Similar with the effects of hypoxia on other TLRs in other cell types, hypoxia also up-regulates TLR9 expression in breast cancer cells in vitro and in orthotopic breast tumors in vivo." (PMID 25101078, 2014). "Although hypoxia also induces TLR9 expression in breast cancer cells, we previously demonstrated, particularly in triple-negative breast cancers, that decreased TLR9 expression does not inhibit hypoxia-induced invasion but rather augments it." (PMID 24959259, 2014). "Functional TLR9 have also been found in many human epithelial cancer cells such as lung cancer, breast cancer and prostate cancer." (PMID 23251529, 2012).
breast cancer (continued). "Estrogens have been reported to induce the down regulation of TLR9 expression in Estrogen Receptor (ER)+ breast cancer cell lines, but nothing has been reported regarding the expression and function of TLR9 on myeloid and lymphoid cells." (PMID 22768144, 2012). "Another study highlights the role of TLR9 in highly invasive MDA-MB-231 breast cancer cell line which when activated promotes MDA-MB-231 cell invasion by increasing the activity of matrix metalloproteinase 13 (MMP13), but not MMP8." (PMID 22295250, 2012). "Expression of TLR9 and its invasive effects on breast cancer cells has been found to be regulated by estrogen receptor-α (ERα) and sex steroid hormones." (PMID 22295250, 2012). "In breast cancer it has been demonstrated that immunoexpression of TLR9 is significantly increased in high-grade tumours compared with lower-grade tumours." (PMID 21929816, 2011). "Stimulation of TLR9-expressing breast cancer cells with the TLR9 agonistic CpG oligonucleotides dramatically increased their in vitro invasion capacity in both Matrigel assays and three-dimensional collagen cultures." (PMID 20618976, 2010). "The purpose of the present study was to investigate the expression of TLR3, TLR4 and TLR9 in breast cancer as well as its relation to distant metastasis." (PMID 21129170, 2010). "The highly invasive MDA-MB-231 breast cancer cell line expresses TLR9, which promotes tumour cell invasion by increasing the activity of MMP-13." (PMID 20145615, 2010). "For examples, Gram-positive bacterium Listeria monocytogene accelerated mouse hepatocarcinoma cell H22 growth via TLR2 signaling; TLR9 agonist CpG ODN promotes breast cancer cell MDA-MB-231 to activation of invasion via increased MMP9 secretion." (PMID 20520770, 2010). "The expression levels of TLR3, TLR4 and TLR9 have clinical interest as indicators of tumor aggressiveness in breast cancer." (PMID 21129170, 2010). "The expression levels of TLR3, TLR4 and TLR9 were analyzed on tumors from 74 patients with breast cancer." (PMID 21129170, 2010). "Consequently, TLR-3, TLR-6, TLR7/8, and TLR-9 agonists are considered among the most promising immunotherapeutic agents for breast cancer treatment." (PMID 41550509, 2026). "Patients with stage 2–3 HER2-negative breast cancer were randomized to weekly paclitaxel (control), weekly paclitaxel and pembrolizumab, or weekly paclitaxel, pembrolizumab and intra-tumoral injection of SD-101, a TLR9 agonist." (PMID 39305392, 2025). "The aim of this study was therefore to investigate whether HPV infections could also regulate TLR9 expression also in breast cancer." (PMID 39644451, 2024). "Conditions used for the current experiments (1% O2) surprisingly demonstrated TLR9 mRNA suppression, and lower O2 level might actually better mimic the conditions in the breast cancer microenvironment." (PMID 39644451, 2024). "Low TLR9 expression has been linked to an aggressive subtype of triple-negative breast cancer and poor disease-specific survival in patients with triple-negative breast cancer, indicating that TLR9 expression is favorable for the patient prognosis with this type of breast cancer." (PMID 38903515, 2024). "Regulation of TLR9 expression in breast cancer is poorly understood." (PMID 39644451, 2024). "We show here that HPV16 E6 does regulate TLR9 transcripts also in breast cancer cells." (PMID 39644451, 2024). "TLR9 signaling has also been found to promote tumor progression in lung cancer and colorectal cancer, and accelerate cell invasion in prostate, ovarian, and breast cancer." (PMID 38850110, 2024). "The anti-tumor effects of TLR9 activation may depend on factors such as the dose and type of the ligand, the tumor microenvironment, and the breast cancer subtype." (PMID 38903515, 2024). "Moreover, the expression of TLR9 has been investigated in relation to lymph node metastasis in breast cancer, with positive TLR9 status potentially serving as an indicator of poor prognosis." (PMID 38903515, 2024).
breast cancer (continued). "It is currently unclear whether TLR9 is only a prognostic biomarker, or whether it has a role in breast cancer pathophysiology or treatment responses." (PMID 39644451, 2024). "The expression and functional role of TLR9 in breast cancer may vary across different breast cancer subtypes." (PMID 38903515, 2024). "In conclusion, these results suggest that HPV16 infections may regulate TLR9 transcripts in breast cancer cells." (PMID 39644451, 2024). "HPV16 may influence breast cancer cell TLR9 transcription and chemotherapy responses and could thereby affect breast cancer prognosis." (PMID 39644451, 2024). "Furthermore, CpG oligonucleotides, known to stimulate TLR9, have been shown to induce invasion in breast cancer cells." (PMID 38903515, 2024). "It is known that hypoxia, ERα and testosterone affect TLR9 expression in breast cancer cells." (PMID 39644451, 2024). "Conversely, there is evidence suggesting that TLR9 activation may have anti-tumor effects in breast cancer." (PMID 38903515, 2024). "Similarly, mtDNA-containing EVs produced by breast cancer cells can enable the intercellular transfer of invasive behavior to promote breast cancer invasion by activating Toll-like receptor 9 (TLR9) in recipient cells." (PMID 37569723, 2023). "Furthermore, HIFU upregulated multiple innate immune receptors and immune pathways when combined with checkpoint modulator anti-PD-1 and toll-like receptor 9 agonist CpG in mice with breast cancer." (PMID 34943854, 2021). "In this study, we found that cfDNA from breast cancer cells not only could activate the TLR9-NF-κB pathway, but also increased the amount of p-ERα in HR+ breast cancer cells, ultimately increasing the abundance of cyclin D1." (PMID 28574818, 2017). "Despite that aggregation analyses did not indicate a breast cancer association with particular TLR9 variant classes, there were more rare coding variants reported in individuals diagnosed over the age of 45 compared to under 45 years of age." (PMID 28886076, 2017). "Similar analyses comparing AA breast cancer cases with AA controls did not reveal any variant class differences; however, three previously unreported TLR9 variants were associated with late onset breast cancer." (PMID 28886076, 2017). "Collectively, we showed that cfDNA could promote the proliferation of HR+ breast cancer cells via the TLR9-NF-κB-cyclin D1 pathway." (PMID 28574818, 2017). "We compared bisphosphonate effects in breast cancer cell lines with low or high TLR9 expression." (PMID 27888633, 2016). "On the contrary, other studies pointed out that e.g., silencing of TLR4 increased tumor progression and lung metastases in a murine model of breast cancer and that TLR9 agonists could induce apoptosis in A20 lymphoma cells and neuroblastoma cells." (PMID 27187369, 2016). "We have previously demonstrated that TLR9 is widely expressed in breast cancers." (PMID 27888633, 2016). "Similarly, both pamidronate and alendronate were stronger inducers of growth inhibition in TLR9 shRNA 4T1 mouse mammary carcinoma cells, as compared with the corresponding control shRNA cells." (PMID 27888633, 2016). "In addition to cells of the immune system, TLR9 mRNA and protein are also widely expressed in breast cancer cell lines and in clinical breast cancer specimens." (PMID 25101078, 2014). "Although TLR9 is expressed in all clinically relevant subtypes of breast cancer, we and others have discovered that there is an inverse correlation between tumor TLR9 and ER expression: ER-positive breast cancers have significantly lower levels of TLR9 expression, as compared with TNBCs." (PMID 25101078, 2014). "TLR-9 expression has also been reported in normal human epithelia, including airway epithelium and intestinal epithelium, as wells as in human tumor tissues and cells, including breast cancer and cervical squamous cell carcinoma." (PMID 28548068, 2014).
breast cancer (continued). "Consistent with the endosomal/lysosomal localization of TLR9 at the subcellular level, in breast cancer cells in vitro, TLR9 appeared punctate in intracellular fluorescence staining, located especially in the perinuclear region, where these organelles are located." (PMID 25101078, 2014). "Our previous studies with breast cancer cells further suggested that TLR9 expression may regulate cancer cell invasion, even in the absence of ligands." (PMID 23761830, 2013). "In breast cancer cells, TLR9 expression is upregulated by sex steroids and bicalutamide." (PMID 23761830, 2013). "On the contrary, we recently demonstrated that absent or low TLR9 expression in tumors is associated with poor prognosis in patients with renal cell carcinoma or triple-negative breast cancer, however not in ER+ breast cancer patients." (PMID 23761830, 2013). "Expression of TLR9 isoforms A and B have been detected in clinical breast cancer specimens." (PMID 22295250, 2012). "Similarly, it has been shown that recurrent breast carcinomas exhibit a significant increase in the mRNA levels of TLR9 in cancer cells." (PMID 21929816, 2011). "Our results show high expression of TLR3, TLR4 and TLR9 by breast cancer cells though." (PMID 21129170, 2010). "Also, differences between TLR9 expression and breast cancer subtypes/stages were detected." (PMID 39644451, 2024). "However, regulation of TLR9 expression in breast cancer is only superficially understood." (PMID 39644451, 2024). "Hence, ccfDNA could stimulate the proliferation of HR+ breast cancer cells by activating the pathway TLR9-nuclear factor kappa B-cyclin D1 pathway." (PMID 33578793, 2021). "Moreover, the up‐regulation of TLR3, TLR4 and TLR9 expressions could increase the probability of biochemical recurrence and cancer metastasis in prostate and breast cancer, respectively." (PMID 33336901, 2021). "Our efforts to test an association of germline TLR9 variants with AA breast cancer risk did not reveal any variant class differences between cases and controls; however, three previously unreported TLR9 variants appears to be slightly associated with late (>45 years) onset breast cancer." (PMID 28886076, 2017). "Thus, we showed that cfDNA could promote HR+ breast cancer cell proliferation by activating the TLR9-NF-κB pathway directly and indirectly." (PMID 28574818, 2017). "Furthermore, we showed cfDNA could promote HR+ breast cancer cell proliferation by activating the TLR9-NF-κB-cyclin D1 pathway." (PMID 28574818, 2017). "In addition, cfDNA could stimulate the proliferation of HR+ breast cancer cells by activating the TLR9-NF-κB-cyclin D1 pathway." (PMID 28574818, 2017). "Furthermore, we observed that cfDNA could promote the proliferation of hormone receptor positive (HR+) breast cancer cells by the activating toll-like receptor 9 (TLR9)-nuclear factor kappa B (NF-κB)-cyclin D1 pathway." (PMID 28574818, 2017). "Therefore, declining hormone levels could result in decreased TLR9 expression in breast cancer cells." (PMID 27888633, 2016). "Furthermore, ERα and sex steroids regulate TLR9 expression in breast cancer." (PMID 27888633, 2016). "Furthermore, although we demonstrated that low-TLR9–TNBC cells become highly invasive in hypoxic conditions, it is currently unclear whether this mechanism contributes to the poor survival of the breast cancer patients that have hypoxic, low-TLR9–TNBC tumors." (PMID 25101078, 2014). "However, expression studies have found breast cancer patients to have high levels of TLR9." (PMID 23634849, 2013). "In contrast, breast cancer CD44+/CD24−/low CIC have dysregulated innate immune responses featuring dysfunctional virus recognition caused by impaired trafficking of TLR9 and cofactor MyD88 and the absence of TLR2, having a deleterious impact on TLR pattern recognition receptor signaling." (PMID 21079774, 2010). "Thus, hypoxia alone may be one explanation for low TLR9 expression levels in some breast cancers." (PMID 39644451, 2024).